NFATC1 (nuclear factor of activated T cells 1)
Diseases named in the same sentence as NFATC1 in open-access papers (continued):
Sharing a sentence is not in itself a finding about the gene and the disease.
pancreatic cancer (continued). "Accordingly, concomitant expression of NFATc1 and EZH2 was also detected in invasive pancreatic tumors of the fast-progressing KPC model and in a PDAC Patient-Derived Xenograft (PDX) model." (PMID 34943970, 2021). "In the pancreatic cancer cell line PANC-1, NFATc1 knockdown clearly induces DDIAS depletion and results in growth inhibition, indicating the NFATc1-mediated control of DDIAS expression." (PMID 26740967, 2015). "We also demonstrated that NFATc1-mediated resistance can be overcome by cyclosporin A (CsA), an NFAT inhibitor, and that the combination of P-S and CsA synergistically inhibited pancreatic cancer cell growth." (PMID 24284479, 2014). "The dual nature of Orai3 regulation by NFATc1 depends on the non-metastatic v/s metastatic nature of pancreatic cancer cell lines." (PMID 41023307, 2025). "The dual role of NFATc1 as a repressor and activator of MARCH8 in pancreatic cancer cells depending on the cell type points out that there could be epigenetic differences in the MARCH8 promoter region." (PMID 41023307, 2025). "To delineate the role of NFATc1 in regulating Orai3 expression and function, we chose six human pancreatic cancer cell lines: MiaPaCa-2 and BxPC-3 (non-metastatic), PANC-1 and AsPC-1 (invasive), and CFPAC-1 and SW1990 (metastatic)." (PMID 41023307, 2025). "Our data demonstrate that NFATc1 positively regulates Orai3 transcription in non-metastatic pancreatic cancer cells." (PMID 41023307, 2025). "Interestingly, the NFATc1 overexpression and NFAT inhibition studies in pancreatic cancer cell lines showed a surprising dichotomy in the regulation of Orai3 by NFATc1 in non-metastatic v/s invasive and metastatic cells." (PMID 41023307, 2025). "We demonstrate that NFATc1 drives Orai3 transcription in non-metastatic pancreatic cancer cells." (PMID 41023307, 2025). "To further substantiate this hypothesis, we selected three more pancreatic cancer cell lines BxPC-3 (non-metastatic), AsPC-1 (invasive), and SW1990 (metastatic) for performing NFATc1 loss and gain-of-function experiments." (PMID 41023307, 2025). "Therefore, both siRNA-mediated NFATc1 knockdown and competitive inhibition of NFAT display the dichotomous regulation of Orai3 in non-metastatic v/s metastatic pancreatic cancer cells." (PMID 41023307, 2025).
Arthritis (16 papers, 2007 to 2026). Inflammation of a joint. "Increase systemic bone mass via inducing the reprogramming of osteoclasts metabolism, enhancing glycolysis, and down-regulating TRAF6 and NFATc1;Prevent bone loss after menopause;Alleviate arthritis." (PMID 36140990, 2022). "Our research group had already shown that osteostatin modulates osteoclastogenesis through NFATc1 inhibition, as well as its anti-inflammatory potential in osteoarthritic osteoblasts and collagen-induced arthritis in mice." (PMID 38474000, 2024). "Published research showed that excavatolide B (2.5 and 5 mg/kg, s.c.)in adjuvant (AIA) and type II collagen-induced arthritis in rats attenuate the protein expression of CD11b and nuclear factor of activated T cells 1 (NFATc1) in ankle tissues." (PMID 35368757, 2022). "In this model of postmenopausal arthritis, YSJB administration improved arthritis progression and prevented bone destruction by reducing osteoclastogenesis and regulating the expression of ephrinB2, ephB4, and NFATc1 in the BM." (PMID 36249763, 2022). "We characterized one potential mechanism by which Nampt affects arthritis through its transcriptional regulation of the osteoclastogenesis essential transcription factor Nfatc1." (PMID 30774990, 2019). "After IFN-β administration, the arthritis scores were decreased; synovial inflammation, cartilage, and bone destruction were clearly attenuated; and the expression of c-Fos and NFATc1 were reduced, while RANKL and TRAF6 expression was unchanged." (PMID 25491303, 2014). "In vitro assays revealed impaired osteoclastogenesis in Nampt-deficient RAW 264.7 and BMM which corresponded with epigenetic suppression of Nfatc1 transcription and may provide a potential mechanism by which the Nampt–NfatC1–osteoclastogenesis pathway promotes arthritis." (PMID 30774990, 2019). "We demonstrate that NFATc1 directly binds the MTHFD2 promoter region, driving metabolic reprogramming in activated T cells from rheumatoid arthritis (RA) patients as well as in experimental arthritis models." (PMID 42270592, 2026). "Although β-glucan-mediated TRIM induction (without secondary arthritis challenge) did not affect CD115+CD27high and CD115+CD27low/− OCP abundance, Nfatc1 expression was significantly upregulated in both populations upon TRIM induction." (PMID 40020679, 2025).
lung carcinoma (16 papers, 2015 to 2025). "NFATc1 expression was also associated with poor prognosis in patients with gastric and lung cancers." (PMID 41203626, 2025). "In lung cancer cells, NFATc1 transcribes the DNA damage–induced apoptosis suppressor, which in turn inhibits cisplatin-induced apoptosis." (PMID 38803221, 2024). "NFATc1 is highly expressed in lung cancer and promotes lung cancer cell survival and epithelial-mesenchymal transition." (PMID 33859351, 2021). "DGG-100629 displayed effective anticancer activity, both in vitro and in vivo, in lung cancer cells expressing high levels of NFATc1 and DDIAS and exhibiting gefitinib resistance." (PMID 33859351, 2021). "Therefore, targeting DDIAS or NFATc1 inhibits the mechanism(s) involved in regulating cisplatin resistance in lung cancer cells." (PMID 37121974, 2023). "Moreover, by promoting the expression of multiple target genes, including DDIAS, cyclin D1, IL-2, and IL-4, NFATc1 protects lung cancer cells against anticancer drug-induced death." (PMID 33859351, 2021). "Additionally, ectopic expression of miR-338 has been shown to restrict the proliferative activities and epithelial-mesenchymal transition of lung cancers, which was realized through downregulating its target NFATc1." (PMID 33882457, 2021). "Moreover, DGG-100629 inhibited the growth of lung cancer patient-derived gefitinib-resistant cells expressing NFATc1 and DDIAS." (PMID 33859351, 2021). "Our data may suggest a novel strategy for the treatment of gefitinib-resistant lung cancers with high expression of NFATc1 and DDIAS." (PMID 33859351, 2021). "To further study which miRNA regulated NFATc1 expression, we predicted several miRNAs including miR‐143, miR‐124, miR‐338, miR‐137, and miR‐218 by online database TargetScan 7.2, and these five miRNAs acted as tumor suppressor in lung cancer." (PMID 31823518, 2020). "Our data provide mechanistic insights into the tumorigenic effects of DDIAS, linking NFATc1 function in immune cells to the role of STAT3 in the proliferation and survival of lung cancer cells." (PMID 33859351, 2021). "Notably, NFATc1 expression was significantly and positively correlated with MDM2 levels in multiple cancer types, including CRC, gastric cancer, and lung cancer." (PMID 41203626, 2025). "Interestingly, we found that the expression of NFATc1 and DDIAS was elevated in H23 and H1703 cells, as well as in four gefitinib-resistant PDCs, but was downregulated in gefitinib-sensitive lung cancer cells, such as H358 and Calu-3 cells." (PMID 33859351, 2021). "Moreover, DGG-100629 reduced the proliferation of gefitinib-resistant lung cancer cells isolated from patients who expressed high levels of NFATc1 and DDIAS, suggesting that blocking DDIAS transcription is a unique approach for the treatment of gefitinib-resistant lung cancer." (PMID 37121974, 2023). "On the other hand, we have shown NFATc1 inhibition does not result in SOX2 suppression, indicating NFATc2 is likely to be preferentially involved in lung cancers." (PMID 28737489, 2017).
periodontitis (15 papers, 2019 to 2026). An acute or chronic inflammatory process that affects the tissues that surround and support the teeth. "In a mouse periodontitis model, males demonstrated greater osteoclastogenesis and chemokine expression, and they were associated with higher Nfatc1 expression." (PMID 36046680, 2022). "In periodontitis, key transcription factors, such as c-Fos, NFATc1, and c-Src play pivotal roles in promoting inflammation and pathological bone resorption by enhancing osteoclastogenesis." (PMID 41484074, 2026). "paeonol protected against periodontitis-aggravated osteoclastogenesis and alveolar bone lesion via regulating Nrf2/NF-κB/NFATc1 signaling pathway." (PMID 38800469, 2024). "Relative mRNA expression levels of PI3K, Acp5, and NFATc1 in the normal human periodontal ligament and chronic periodontitis were analyzed by quantitative reverse-transcription polymerase chain reaction." (PMID 36979821, 2023). "Our results showed that PI3K was consistent with Acp 5 and NFATc1 in that they were all highly expressed in human chronic apical periodontitis tissues." (PMID 35953782, 2022). "The relative mRNA expression of PI3K, Acp5 and NFATc1 in the normal human periodontal ligament and in chronic apical periodontitis were analyzed by real-time quantitative polymerase chain reaction (RT-qPCR)." (PMID 35953782, 2022). "The expression of PI3K (P = 0.009), Acp5 (P < 0.001) and NFATc1 (P = 0.003) genes were all higher in the chronic apical periodontitis samples than in healthy periodontal ligament tissue, and the difference was statistically significant." (PMID 35953782, 2022). "The expression of PI3K, Acp5 and NFATc1 genes in chronic apical periodontitis sample groups was significantly increased relative to healthy periodontal ligament tissue (P < 0.05)." (PMID 35953782, 2022). "After 14 days of periodontitis induction, the WT-ligature mice showed an increased expression of osteoclast markers Trap, Ctsk, Dcstamp, and Nfatc1 and decreased expression of osteoblast markers Runx2, Alp, Opn, and Osx, compared with the WT-sham group." (PMID 33869229, 2021). "For example, paeonol exhibited protective effects against periodontitis through regulation of the Nrf2/NF‐κB/NFATc1 signaling pathway." (PMID 32687664, 2020). "Therefore, calcitriol intervention could be a useful measure to attenuate bone resorption in periodontitis by reducing NFATc1 and MMP‐9." (PMID 32406154, 2020). "During periodontitis, increased RANKL levels lead to upregulation of NFATc1, driving osteoclast differentiation and alveolar bone resorption." (PMID 41484074, 2026). "Both JQ1 and I-BET151 were small molecule inhibitors for BET proteins and JQ1 was demonstrated to attenuate inflammation and bone destruction in experimental periodontitis via neutralizing BRD4 enrichment at NF-κB, TNF-α, c-Fos, and NFATc1." (PMID 30455393, 2019). "Consistently, our results show that c-Fos and NFATc1 protein expression levels were significantly increased by PgLPS while decreased by KMUP-1, suggesting that KMUP-1 may protect against periodontitis." (PMID 35571109, 2022). "In addition, high HIF-1α and NFATc1 levels were detected in severe periodontitis and gingival crevicular fluid samples of severe periodontitis patients, suggesting a role for the TNF-α/HIF-1α/VEGF pathway in the pathogenesis of periodontitis." (PMID 36142220, 2022).
cardiac hypertrophy (13 papers, 2011 to 2025). "Systemic arterial pressure was lower in Tie2-L613V or Nfatc1-L613V mice than in controls, excluding hypertension as the cause of cardiac hypertrophy." (PMID 28548091, 2017). "To address the molecular basis of the restored cardiac dimensions of splice-rescue mice, we analyzed the expression of several proteins previously linked to cardiac hypertrophy signaling such as Erk1/2, Akt, mTOR, NFATc1, and JNK." (PMID 27889803, 2016). "Four distinct genes encoding closely related NFATc proteins (NFATc1–4) have been identified and are involved in multiple biological processes ranging from lymphocyte activation and development to cardiac hypertrophy." (PMID 21603612, 2011). "We explored the role of circCacna1c in the regulation of cardiac hypertrophy by targeting the miR-29b-2-5p/NFATc1 axis in the heart." (PMID 37371137, 2023). "Silencing circCacna1c and the overexpression of miR-29b-2-5p can effectively block cardiac hypertrophy by decreasing the expression of NFATc1." (PMID 37371137, 2023). "In conclusion, our experiments indicate that circCacna1c could be acting as miR-29b-2-5p sponge to regulate NFATc1 in cardiac hypertrophy." (PMID 37371137, 2023). "Here, we aimed at neutralizing four members of the NFAT family of transcription factors as a therapeutic strategy for myocardial hypertrophy transiting to heart failure through AAV-mediated cardiac expression of a RNA-based decoy oligonucleotide (dON) targeting NFATc1-c4." (PMID 34089101, 2021). "Our study provides a novel and effective therapeutic option for cardiac hypertrophy and heart failure, consisting of AAV-mediated delivery of a RNA-based dON neutralizing transcriptional activity of the NFATc1-c4 family of transcription factors." (PMID 34089101, 2021).
prostate carcinoma (12 papers, 2010 to 2024). A carcinoma that arises from epithelial cells of the prostate gland. "Therefore, we identified and mutated the PIM targets sites from NFATC1 and analysed the impact of these mutations in three prostate cancer cell lines, the hormone-insensitive PC-3 and DU-145 cells and the hormone-sensitive LNCaP cells." (PMID 31730483, 2019). "Prostate-cancer-cell-derived EVs loaded with miR-378a-3p accelerated osteolysis by targeting the Dyrk1a/Nfatc1 axis to upregulate ANGPTL2 expression and secretion, thereby promoting PMN formation and enhancing prostate cancer metastasis." (PMID 37046819, 2023). "Prostate cancer is most likely to develop bone metastases, and prostate cancer-derived miR-378a-3p-containing EVs promote osteolysis by activating the Dyrk1a/Nfatc1/Angptl2 axis in bone marrow macrophages during tumor bone metastasis." (PMID 38037077, 2023). "NFATc1 is overexpressed in prostate cancer cells, and its inhibition suppresses aerobic glycolysis, concurrent with a decrease of pyruvate kinase 2 (PKM2)." (PMID 36077186, 2022). "We also performed a microarray analysis to identify novel PIM1/NFATC1 targets, and validated one of them with both cellular expression analyses and in silico in clinical prostate cancer data sets." (PMID 31730483, 2019). "Here we have identified ten PIM1 target sites in NFATC1 and found that prevention of their phosphorylation significantly decreases the transcriptional activity as well as the pro-migratory and pro-invasive effects of NFATC1 in prostate cancer cells." (PMID 31730483, 2019). "As we had previously shown both PIM kinases and NFATC1 to be essential for the motility of PC-3 prostate cancer cells, we decided to use these cells in order to investigate in more detail the functional interactions between PIM and NFATC1 proteins." (PMID 31730483, 2019). "These include the ITGA5 integrin, which is differentially expressed in the presence of wild-type versus phosphorylation-deficient NFATC1, and which is coexpressed with PIM1 and NFATC1 in clinical prostate cancer specimens." (PMID 31730483, 2019). "We used mass spectrometry to identify PIM1 phosphorylation target sites in NFATC1, and analysed their functional roles in three prostate cancer cell lines by comparing phosphodeficient mutants to wild-type NFATC1." (PMID 31730483, 2019). "NFATC1 has been shown to support cell migration or invasion in multiple types of cancer, such as ovarian, breast and prostate cancer as well as glioblastoma." (PMID 31730483, 2019). "Here we have investigated the signaling pathways that support migration and invasion of prostate cancer cells, focusing on the role of the NFATC1 transcription factor and its post-translational modifications." (PMID 31730483, 2019). "In conclusion, we have shown that phosphorylation of PIM1 target sites stimulates the transcriptional activity of NFATC1 and enhances its ability to promote prostate cancer cell migration and invasion." (PMID 31730483, 2019). "Similar wound healing experiments were also performed with DU-145 prostate cancer cells, which transiently overexpressed WT NFATC1 or the multi mutant." (PMID 31730483, 2019). "Based on our data, phosphorylation of PIM1 target sites stimulates NFATC1 activity and enhances its ability to promote prostate cancer cell migration and invasion." (PMID 31730483, 2019). "Here we have analysed the functional interactions of PIM and NFATC1 proteins in several prostate cancer cell lines." (PMID 31730483, 2019). "Our data demonstrate that soluble factors produced by prostate cancer cells induce osteoclast formation through activation of calcium/NFATc1 and MEK/ERK signaling pathways." (PMID 24370273, 2013). "Inhibition of NFATc1 using cell-permeable peptide inhibitor VIVIT significantly interfered with the ability of prostate cancer-derived factors to induce osteoclastogenesis." (PMID 24370273, 2013).